GATA4 (GATA binding protein 4)
Diseases named in the same sentence as GATA4 in open-access papers (continued):
Sharing a sentence is not in itself a finding about the gene and the disease.
dilated cardiomyopathy (7 papers, 2015 to 2025). Cardiomyopathy which is characterized by dilation and contractile dysfunction of the left and right ventricles. "Apart from several CHDs, loss-of-function mutations in GATA4 and GAT5 contribute to neonatal dilated cardiomyopathy that can lead to congestive heart failure and sudden cardiac failure, which is the primary reason for transplants in affected individuals." (PMID 40076735, 2025). "Also variants in transcription factor genes, such as GATA4 and TBX20, have been associated with both CHD and dilated cardiomyopathy." (PMID 33194928, 2020). "Rapid death of these mice was surprising given that mice with fetal Gata4/6 inactivation by Myh7-Cre (also known as MHCβ-Cre) survived normally through the neonatal period and into adulthood, when they died by ~100 days of age from dilated cardiomyopathy." (PMID 26023924, 2015). "GATA4 is a critical regulator of cardiac differentiation; FOG2/ZFPM2 is essential for heart morphogenesis and coronary development; FOS is significantly activated in dilated cardiomyopathy." (PMID 38474301, 2024).
Obesity (7 papers, 2012 to 2025). Accumulation of substantial excess body fat. "The loss of intestinal GATA4 prevents diet-induced obesity, promotes insulin sensitivity, and protects against diet-induced hepatic steatosis in mice." (PMID 41190635, 2025). "Mice with an intestine-specific GATA4 deficiency (GATA4iKO) are resistant to diet-induced obesity and insulin resistance." (PMID 22750465, 2012). "Alternatively, ASBT upregulation might be regulated either by the upregulation of FXR expression or downregulation of GATA4 along the length of the small intestine in obesity." (PMID 39519005, 2024). "In this study, the increased ASBT expression might be facilitated by altered GATA4 and/or FXR expressions along the length of the small intestine in obesity." (PMID 39519005, 2024). "CUX1, NANOG, GATA4 and HIF1A plays a vital role in the patients with obesity." (PMID 36837510, 2023).
alcohol dependence (6 papers, 2013 to 2024). Physical and psychological dependence on alcohol. "GATA4 was identified in both 5mC and 5hmC differential analyses and has been previously associated with alcohol dependence." (PMID 38633406, 2024). "A genome-wide association study (GWAS) revealed alcohol dependence to be associated with a single-nucleotide polymorphism located in gene GATA4, which encodes a transcription factor regulating ANP." (PMID 25506340, 2014). "A significant association between GATA4 and alcohol dependence at the gene level was demonstrated." (PMID 24367640, 2013). "GATA4 was suggested to regulate atrial natriuretic peptide (ANP, officially known as NPPA) modulating the amygdala’s response to alcohol dependence and is associated with BP." (PMID 29912962, 2018).
Barrett esophagus (6 papers, 2008 to 2021). Esophageal lesion lined with columnar metaplastic epithelium which is flat or villiform. "By contrast, expression of SOX2 remained suppressed, whereas expression of GATA4 was upregulated in Barrett’s metaplasia, suggesting that Barrett’s metaplasia exhibits a transcription pattern similar to that of primitive transitional epithelial cells." (PMID 33495473, 2021). "GATA4 mRNA up-regulation and gene amplification occur in BE and its associated cancer, esophageal adenocarcinoma (EAC), and GATA4 gene amplification correlates with poor patient outcomes." (PMID 33547361, 2021). "GATA4 and GATA6 were previously implicated in EAC by the numerous studies that have observed that their loci are frequently amplified in the transition from Barrett's esophagus to cancer." (PMID 30962179, 2019). "Notably, among gastrointestinal cancers, GATA4 is amplified in ∼10% of esophageal adenocarcinomas and Barrett metaplasia." (PMID 22719836, 2012). "Interestingly, the expression of GATA-4, GATA-6 and Ihh appear to increase in two precancerous lesions such as Barrett's esophagus and intestinal metaplasias of the stomach." (PMID 18405344, 2008). "Barrett's esophagus (data not shown) as well as intestinal metaplasia of the stomach were nevertheless highly positive for GATA-4, GATA-6 and Ihh (4A', and 4A")." (PMID 18405344, 2008).
embryonal carcinoma (6 papers, 2013 to 2021). A non-seminomatous malignant germ cell tumor characterized by the presence of large germ cells with abundant cytoplasm resembling epithelial cells, geographic necrosis, high mitotic activity, and pseudoglandular and pseudopapillary structures formation. "Stat-3 and Ras pathways have been implicated in the control of GATA-4 expression in embryonal carcinoma and ES cells, and experiments using GATA-6 knockout and chimeric mice suggest a cross-regulation between GATA-6 and GATA-4." (PMID 23409073, 2013). "Gata4 expression is upregulated by exogenous FGF1 in response to cardiac genes in differentiating embryonic carcinoma cell cultures, and Afp expression is dependent on FGFs that are produced by the cardiac mesoderm in embryonic endoderm cells." (PMID 23874841, 2013). "Hdac1 depletion stimulated cardiomyocyte formation, increased the levels of acetylated lysines and upregulated the expressions of GATA4 and NKX2.5 in ES cells and embryonal carcinoma cells." (PMID 33882103, 2021).
glioblastoma (6 papers, 2013 to 2023). The most malignant astrocytic tumor (WHO grade IV). "In this study, we investigated methylation of GATA4 and DcR1 promoters and their association with patient prognosis in glioblastoma." (PMID 23320456, 2013). "As an alternative to deletion GATA4 and DcR1 promoter methylation may be associated with clinical data of glioblastoma patients." (PMID 23320456, 2013). "In glioblastoma multiforme (GBM), loss of GATA4 was observed in 58 % (94/163) of GBM operative samples and was found to be a negative survival prognostic marker." (PMID 26490736, 2015). "Previous studies have nominated GATA4 as a candidate tumor suppressor gene in part because GATA4 experiences promoter hypermethylation in glioblastoma, ovarian, endometrial, and colorectal carcinomas." (PMID 35017504, 2022). "The methylation status of the GATA4 and DcR1 promoter in glioblastoma samples was detected by methylation-specific PCR assay." (PMID 23320456, 2013). "Methylation status of GATA4 and DcR1 promoters was investigated by methylation specific PCR in 99 glioblastoma patients." (PMID 23320456, 2013). "To analyze the potential of GATA4 as methylation marker in glioblastoma, we analyzed large series of glioblastoma tumor samples and one normal brain tissue." (PMID 23320456, 2013). "In order to identify molecular markers relevant to glioblastoma development, diagnosis and prognosis promoter methylation analysis of 2 genes, DcR1 and GATA4, was performed." (PMID 23320456, 2013). "In conclusion, the present work demonstrated that GATA4 and DcR1 promoter hypermethylation is tumor specific event in glioblastoma but they promoter methylation cannot be considered as a prognostic marker in glioblastoma." (PMID 23320456, 2013). "We evaluated methylation status of the GATA4 promoter in 95 glioblastoma tumors." (PMID 23320456, 2013). "The present work demonstrated that GATA4 and DcR1 promoter hypermethylation is tumor specific event in glioblastoma but they promoter methylation cannot be considered as a prognostic marker of glioblastoma survival." (PMID 23320456, 2013). "In this study, we evaluated the methylation status of GATA4 and DcR1 promoters in glioblastoma tumor tissue to support the hypothesis that they are inactivated in glioblastomas by promoter hypermethylation and plays a role as tumor suppressor genes in gliomagenesis." (PMID 23320456, 2013). "Loss of expression of GATA4 and GATA6 occurs in glioblastoma multiforme (GBM)." (PMID 26953528, 2016). "A previous investigation of the methylation status of GATA4 promoters by methylation-specific PCR in 99 glioblastoma patients showed that GATA4 was aberrantly methylated in 23.2 % of glioblastoma tumors, but not in normal brain." (PMID 26490736, 2015). "GATA4 alone has no influence on survival time in glioblastoma patients." (PMID 37372326, 2023). "However, up to now the methylation frequency of GATA4 and DcR1 genes has not been determined in glioblastoma." (PMID 23320456, 2013).
hepatoblastoma (6 papers, 2016 to 2026). Hepatoblastoma (HB) is a malignant hepatic tumor and is the most common pediatric liver cancer. "Elevated expression of transcription factor GATA4 has been associated with pro-tumorigenic functions in hepatoblastoma." (PMID 41671222, 2026). "Herein, we explored the effects of a novel series of GATA4-targeted compounds (3i-2010-3i-2014) in several hepatoblastoma cell models." (PMID 41671222, 2026). "Another study found that GATA binding protein 4 (GATA4) was highly expressed in hepatoblastoma and correlated with the mesenchymal migration phenotype of hepatoblastoma cells, and that GATA4 gene silencing inhibited the migration of HUH6 cells." (PMID 38033502, 2023). "GATA4 is also highly expressed in most hepatoblastomas and correlates with a mesenchymal, migratory phenotype in hepatoblastoma cells by regulating the expression of ADD3, AHNAK, and IGFBP1." (PMID 33648545, 2021). "The transcription factor GATA4, crucially important in the early liver development, has been shown to be involved in the pathophysiology of hepatoblastoma, an embryonic tumor of childhood." (PMID 32230806, 2020). "Suppression of the GATA4 gene (using RNA interference) disturbed the migration of the human hepatoblastoma cells, HUH6." (PMID 32230806, 2020). "In this study, we demonstrate that GATA4 promotes growth and survival in the Huh6 human hepatoblastoma cell line." (PMID 27788486, 2016). "While AHNAK expression decreased after GATA4 knockdown, overexpression of GATA4 caused AHNAK elevation, suggesting that AHNAK upregulation may promote hepatoblastoma progression." (PMID 38033502, 2023). "Thus, the GATA4/miR125b/DKK3 axis might serve as a novel therapeutic target in pediatric hepatoblastoma patients." (PMID 27788486, 2016). "However, the effects of GATA4 in hepatoblastoma (HB), a common liver cancer in pediatric patients, remain largely unknown." (PMID 27788486, 2016). "Recent transcriptome analyses have unveiled that the genes GATA4, DPEP1 and DRAM1 exhibit high expression levels in hepatoblastoma tumor samples." (PMID 38390281, 2024).
hypospadias (6 papers, 2019 to 2025). Hypospadias is the displacement of the urethral meatus on the ventrum of the penis. "A dual-luciferase reporter assay revealed that the rs12458 variant could create a binding site for miR-556, potentially influencing GATA binding protein 4 (GATA4) expression and increasing hypospadias risk." (PMID 39624466, 2025). "Of the seven individuals with GATA4 variants, five presented with hypospadias (case 2, 3, 5–7)." (PMID 31962012, 2020). "They identified miR-556 as a regulator of GATA4 expression, contributing to the development of hypospadias." (PMID 39624466, 2025). "A recent study confirmed the theory of hypospadias development through apoptosis by demonstrating the regulatory role of miR-556 in the GATA4 expression level." (PMID 39624466, 2025). "A proportion of XY males carrying deletions of 8p23.1 that encompasses the GATA4 gene have hypospadias and bilateral cryptorchidism." (PMID 36631813, 2023). "The GATA4 mutation is usually not found in hypospadias cases; so could it be a fortuitous association?" (PMID 30690934, 2019). "In a study on GATA4, two 46,XY male DSD patients with cryptorchidism, micropenis, and hypospadias without cardiac defects were heterozygous for GATA4 missense variants located close to the GATA4 DNA-binding site, but both variants had wild-type functional activity in vitro." (PMID 32155719, 2020).
Myocardial fibrosis (6 papers, 2020 to 2026). "Nonetheless, previous studies have demonstrated miR-208b may serve a protective role in myocardial fibrosis after infarction through GATA4 signaling." (PMID 35282369, 2022). "Cardiomyocyte hypertrophy and myocardial fibrosis can be treated via the regulation of the miR-485-5p/MAPL/Mfn2 axis and Circ-sh3rf3/GATA-4/miR-29a cascade." (PMID 38515760, 2024).
adenoma (5 papers, 2008 to 2025). A neoplasm arising from the epithelium. "Adenomas with mutant CTNNB1 and all investigated adenomas revealed an unremarkable expression of GATA4." (PMID 28102204, 2017). "No expression of GATA-4 was detected in dysplastic lesions or adenomas of the colon." (PMID 18405344, 2008).
coronary artery disease (5 papers, 2012 to 2021). "It has been reported that GATA4 gene is significantly upregulated in coronary artery disease." (PMID 34193080, 2021). "The abundance and localization of the GATA4 to the myocardial tissue suggests a pivotal cardiovascular functional input, which if perturbed, may lead to various cardiac disorders and coronary artery disease (CAD)-related events." (PMID 24330461, 2013).
granulosa cell tumor (5 papers, 2009 to 2023). A slow-growing, malignant tumor, characterize by the presence of granulosa-like cells and Call-Exner bodies, that is almost always found in the ovary. "Overexpression of GATA4 can protect human granulosa cell tumours from apoptosis induced by TRAIL in vitro." (PMID 34109184, 2021). "The overall good prognosis of juvenile granulosa cell tumors is consistent with their low expression of GATA-4: this factor is probably involved in cell proliferation and its absence may be linked to the better outcome of JGCT." (PMID 23029311, 2012). "Synergistically with GATA-4 it activates the cyclin D2 (CCND2) promoter, a key factor for proliferation and survival in granulosa cell tumors." (PMID 36869369, 2023). "Aberrant ovarian granulosa cell proliferation and apoptosis may lead to granulosa cell tumors (GCT), the pathogenesis of which involves transcription factors GATA4, FOXL2, and SMAD3." (PMID 24416423, 2014). "Intriguingly, juvenile granulosa cell tumors, the more indolent subtype, were mostly negative for GATA-4, but showed a strong expression of FOG-2." (PMID 23029311, 2012). "As previously reported, Inhibin is expressed in the vast majority of cases, except in fibroma-thecoma, where it may be negative; GATA-4 has been recently found to be expressed in adult ovarian GCT and in testis SLCT and to be associated with an aggressive behaviour in adult Granulosa Cell Tumors." (PMID 23029311, 2012).
Infertility (5 papers, 2013 to 2023). "The loss of GATA6 and GATA4 resulted in failed ovulation and infertility, and negatively affected the development of granulosa cells." (PMID 36617567, 2023). "Because GATA4 mutation leads to male sterility, we attempted to rescue the infertile phenotype of the Gata4 cKO mice and thereby identify potential new leads for the treatment of infertile patients carrying a GATA4 mutation." (PMID 26473289, 2015). "This manipulation rescued the infertile phenotype of the Gata4 cKO mice and provided new leads for the treatment of infertile patients carrying a GATA4 mutation." (PMID 26473289, 2015). "In female mice, the loss of GATA4 and GATA6 resulted in failed ovulation and infertility." (PMID 28275215, 2017). "In addition, the loss of GATA4 and GATA6 using knockout technology can lead to abnormal ovarian structure and infertility, including oocyte reduction and ovulation failure." (PMID 28275215, 2017). "GATA4 and GATA6 knockout female mice exhibited infertility due to disrupted formation of ovaries." (PMID 34107878, 2021).
myocardial ischemia (5 papers, 2013 to 2024). A disorder of cardiac function caused by insufficient blood flow to the muscle tissue of the heart. "Therefore, exploring the active ingredients and functional mechanisms of GATA4-Exo is of great significance to developing a new biotherapy of myocardial ischemia based on exosomes." (PMID 32586406, 2020). "This negative feedback pathway is described as that β1-AR is excited and up-regulated in early phase of myocardial ischemia, which activates transcription factor GATA4 via cAMP/PKA signaling pathway, leading to up-regulation of let-7a which inhibits β1-AR expression in CIHF." (PMID 28060734, 2017). "The potential mechanisms might be associated with down-regulated expression of TGF-β1, TNF-α, IL-1β, ASK1, NF-κB Bax, up-regulated expression of Bcl-2 and Gata4, activation of eNOS pathway to ameliorate myocardial ischemia, and enhanced cardiac repair." (PMID 24260217, 2013). "It was also found that global cardiac ischemia/reperfusion injury results in reduced expression of GATA4 in the RV, but not in the LV." (PMID 30096794, 2018). "Consistently, the RV-specific downregulation of GATA4 by ischemia/reperfusion seems to reflect Bcl-xL gene expression, as global myocardial ischemia/reperfusion downregulated Bcl-xL in the RV, but not in the LV." (PMID 30096794, 2018).
pancreatic agenesis (5 papers, 2019 to 2023). Partial agenesis of the pancreas is characterized by the congenital absence of a critical mass of pancreatic tissue. "Three of these (GATA4, GATA6 and HNF4A) are known causes of pancreatic agenesis and/or diabetes in humans when mutated and are involved in endoderm, liver and pancreas specification." (PMID 37973953, 2023). "To date, pathogenic variants in six genes (PTF1A [MIM: 615935], PDX1 [MIM: 260370], GATA6 [MIM: 600001], GATA4 [MIM: 600576], HNF1B [MIM: 137920], and RFX6 [MIM: 615710]) have been reported to severely affect pancreatic development and result in pancreatic agenesis." (PMID 31006513, 2019).
type II diabetes (5 papers, 2012 to 2024). "GATA4 gene mutations may promote the progress of type II diabetes, which may induce inflammation and aging by inhibiting the spontaneous autophagy of GATA4." (PMID 39595537, 2024). "However, the consequences of reduced cardiac GATA4 levels on expression of these structural genes and peptides in the db/db model of type 2 diabetes have not been determined." (PMID 22474596, 2012).
aortic stenosis (4 papers, 2012 to 2026). Aortic valve stenosis is a aortic valve disease caused by the incomplete opening of the aortic valve. "In Gata4+/− mice, a small number of heterozygote mutants were double outlet right ventricle (DORV), and in Gata4+/−;Gata5+/− double heterozygote mutants, almost all embryos were DORV, some of which had further aortic stenosis." (PMID 32843646, 2020).
congenital heart defects (4 papers, 2010 to 2023). "Many GATA4 mutations are associated with congenital heart defects." (PMID 37238360, 2023). "While Gata4 has been shown to be important for several critical processes during heart development, the pathogenesis of heart malformations in humans with the G296S missense mutation in GATA4 is not as well understood." (PMID 22589735, 2012). "Different degrees of GATA4 gene defect have been found to produce ASD in a mouse model, producing a variety of heart malformations." (PMID 25873328, 2015).